ARID1A (AT-rich interaction domain 1A)
Diseases named in the same sentence as ARID1A in open-access papers (continued):
Sharing a sentence is not in itself a finding about the gene and the disease.
breast carcinoma (continued). "Several studies have found that ARID1A downregulation is associated with poor prognosis in luminal breast cancer and mediates treatment responses to tamoxifen and fulvestrant." (PMID 37173914, 2023). "Here, we characterized a subgroup of luminal breast cancer expressing co-mutations in ARID1A and PIK3CA genes and identified their effect on important signaling pathways." (PMID 38017109, 2023). "In a previous study, VEGF mRNA and protein levels also increased in the ARID1A-deficient MCF cells (breast cancer cell line)." (PMID 38017409, 2023). "ARID1A mutations occur in 5% of primary breast cancer but are enriched in endocrine-treatment-resistant tumours and metastases (12%)." (PMID 38275587, 2023). "Two additional SWI/SNF complex members were enriched in our screen, including ARID1A, the loss of which can facilitate hormone therapy resistance in breast cancer." (PMID 37554444, 2023). "A high frequency of ARID1A mutations was detected in luminal breast cancer with a tumor suppressor gene score of 45%." (PMID 35453496, 2022). "Truncating mutations in ARID1A imply loss of function of this SWI/SNF chromatin remodeling complex subunit in ER+ breast cancers." (PMID 35774123, 2022). "Loss of ARID1A inhibits the ER antagonist response and promotes breast cancer recurrence after anti-estrogen therapy." (PMID 35453496, 2022). "Meanwhile, eMDSCs significantly downregulated ARID1A expression in luminal A breast cancer, which was closely associated with EMT and was an important prognostic factor in breast cancer patients." (PMID 36329699, 2022). "The increasing prevalence of ARID1A mutation in endocrine resistant breast cancer, including its prevalence in other cancers, highlights the need of treating ARID1A mutant tumours with targeted therapeutic strategies." (PMID 36212140, 2022). "In breast cancer cells with ARID1A deficiency, ARID1A re-expression is believed to enhance the transcriptional activity through glucocorticoid, estrogen, and estrogen receptors." (PMID 34671561, 2021). "Meanwhile, TEA domain transcription factor 4, which is enriched in basal-like cells, is recruited to accessible sites, indicating the switch of phenotypes from the luminal type to the basal-like type in ARID1A-loss breast cancer." (PMID 34804958, 2021). "ARID1A plays an important pathobiological role in breast cancer, and the partial loss of its expression is associated with unfavorable outcome in patients with breast cancer." (PMID 34671561, 2021). "The increased frequency of ARID1A mutations in endocrine-resistant breast cancer as well as its prevalence in other cancers amplifies the need for targeted therapeutic strategies against ARID1A mutant cancers." (PMID 33741974, 2021). "Previous studies showed that almost 60% breast invasive ductal carcinoma exhibit loss of ARID1A expression and is associated with the most aggressive phenotypes of breast cancer." (PMID 32334542, 2020). "ARID1A mutated carcinomas are associated with poor prognosis, and for instance, in breast cancer patients, inactivated ARID1A suggests a tumor suppressive function." (PMID 33227989, 2020). "In breast cancer model, a loss of ARID1A expression sensitizes cancer cells to PI3K- and AKT-inhibition and knockdown of ARID1A in MCF7 increased pAKT-Ser473 while treatment with MK-2206 increased apoptosis and decreases pS6K in ARID1A-depleted MCF7 cells." (PMID 31731647, 2019). "In HER2 positive breast cancer model, the loss of ARID1A transcriptionally activates annexinA1 (ANXA1)." (PMID 31731647, 2019). "Accordingly, ARID1A down‐regulation appeared to be associated with unfavourable RFS rates in breast cancer patients, based on the K‐M Plotter database." (PMID 29392887, 2018). "ARID1A thus warrants further investigation as a potential diagnostic and therapeutic marker for breast cancer." (PMID 29392887, 2018).
breast carcinoma (continued). "The metastatic breast cancer biopsies in this study are derived from a larger cohort in which ARID1A was found to be significantly mutated and enriched with respect to TCGA26." (PMID 29109393, 2017). "Inactivated mutations and hypermethylation of promoter of ARID1A gene have been reported in breast cancer by several reports." (PMID 26904685, 2016). "The ARID1A gene has been classified as a novel tumor suppressor, as evidenced by associations between ARID1A mRNA or protein expression and several cancers including ovarian, endometrial, gastric, and breast cancers." (PMID 25975202, 2015). "In two independent cohorts of >200 human breast cancer cases, low ARID1A protein expression was associated with more aggressive breast cancer phenotypes, such as those with a high tumor grade." (PMID 25975202, 2015). "Nearly 80% of these breast tumors demonstrated promoter methylation, and the heterozygous and homozygous allelic loss of ARID1A occurred in 35.2 and 2% of cases, respectively, in breast cancer." (PMID 25774356, 2014). "In summary, we found promoter hypermethylation is the main reason for ARID1A gene expression loss in breast cancer." (PMID 23349767, 2013). "One previous study indicates ARID1A gene mutation rate is about 4% in breast cancers, but its copy number loss occurs in 13% in breast cancers reported by the same group and 35% reported by another group, respectively." (PMID 23349767, 2013). "BAF250a as the ARID1A gene product is, however, frequently deficient in tumor tissue samples and breast cancer cell lines, and is thus implicated in the tumor suppressor function of the complexes." (PMID 23349767, 2013). "Among these, the ARID1A gene frequently exhibits copy number loss in breast cancer." (PMID 40671262, 2025). "The authors showed that ARID1A mutations occur in treatment-resistant breast cancer and may provide a rational treatment strategy." (PMID 40650785, 2025). "Decreased ARID1A immunoreactivity was associated with poorer prognosis in breast cancer patients." (PMID 41001036, 2025). "Finally, in highly invasive and metastatic breast cancer cells, the transfection of ARID1A into the cells caused an increase in epithelial marker E-cadherin and a decrease in mesenchymal markers vimentin and N-Cadherin." (PMID 40429787, 2025). "For example, HDAC inhibition might not be a favorable therapeutic option for ARID1A-mutated ER+ breast cancers, as ARID1A-loss-induced endocrine resistance is mediated by the loss of HDAC1 activity." (PMID 41278204, 2025). "Thus, this study highlights the context-dependent role of ARID1A and supports its potential as a diagnostic biomarker and therapeutic target for the treatment management of breast cancer and other malignancies." (PMID 41514650, 2025). "ARID1A is a COSMIC top-20 most frequently mutated gene in breast cancer." (PMID 39885374, 2025). "In this study, ER+ breast cancer cells with ARID1A loss showed increased tumor growth in both untreated and 4-hydroxytamoxifen (a selective estrogen receptor modulator)-treated cells compared to ARID1A wild-type." (PMID 41278204, 2025). "Some studies have used IR to treat ARID1A‐deficient breast cancer cell lines, inducing DNA damage." (PMID 39779467, 2025). "These associations were also detected in ARID1A-mutant breast cancers." (PMID 39482530, 2024). "The prevalence of somatic mutations in MAP2K4 and ARID1A in breast cancer has also been documented in other studies, indicating the presence of a congruent mutational profile within the early-onset Asian breast cancer demographic." (PMID 39482530, 2024). "Indeed, ARID1A deficiency sensitises tumour cells to PARP inhibitors in breast cancer and colorectal cancer cells in vitro and in vivo, and this sensitivity is dependent on the interaction of ARID1A with ATR." (PMID 38275587, 2023).
breast carcinoma (continued). "Recent studies using genome-wide CRISPR screens demonstrate that genes encoding the BAF complex—including ARID1A—mediate therapeutic response to ER antagonists; loss of ARID1A enhances proliferative capacity, rendering ER-positive breast cancer cell lines resistant to both tamoxifen and fulvestrant." (PMID 37568822, 2023). "Moreover, ARID1A protein expression was demonstrated to be an independent prognostic factor in breast cancer, with higher expression associated with better prognosis." (PMID 36890819, 2023). "As a consequence, one can believe that targets EZH2 in breast cancer patients with ARID1A mutations might be a promising treatment option." (PMID 36212140, 2022). "Finally, we proposed a significant role of eMDSCs in promoting EMT of luminal A breast cancer cells by downregulating ARID1A which caused poor prognosis in luminal A breast cancer patients." (PMID 36329699, 2022). "ARID1A is frequently downregulated or mutated in approximately two of three breast cancer cases." (PMID 35453496, 2022). "Inactivating ARID1A mutations were only present in 2.5% of all breast cancers." (PMID 34804958, 2021). "Strikingly, breast cancer patients with tumors harboring ARID1A mutations have a significantly reduced progression-free survival when treated with ER-degrading therapies compared to wild-type ARID1A tumors." (PMID 34680352, 2021). "Moreover, among breast cancers, promoter hypermethylation and histone modification are the main reasons for loss of ARID1A expression." (PMID 32334542, 2020). "Additionally, high levels of ARID1B expression have been linked to poor clinical outcomes in bladder urothelial carcinoma and breast carcinoma, while low ARID1A levels have been linked to poor clinical outcomes." (PMID 31796878, 2019). "Furthermore, the mRNA levels of ARID1A in the high‐risk cohort were significantly down‐regulated compared to the low‐risk cohort in breast cancer patients." (PMID 29392887, 2018). "Thus, we suggest that targeting EZH2 in ARID1A-mutated breast cancer could be a valid therapeutic option to explore." (PMID 33741974, 2021). "However, low ARID1A expression has been found to associate with ER negativity of breast cancer." (PMID 30057548, 2018). "Additionally, ARID1A gene mutations and copy number loss have been reported in some breast cancers." (PMID 23349767, 2013). "This study enhances our understanding of ARID1A regulatory mechanisms, highlighting its phosphorylation as a key driver of breast cancer biology." (PMID 41572083, 2026). "This study employed phosphoproteomic analysis to investigate ARID1A phosphorylation in breast cancer, identifying predominant phosphosites-S363, S1184, and S696-regulated by kinases such as MAPK14, CDK16, and MAPK9." (PMID 41572083, 2026). "Next, we examined differentially expressed genes (DEGs) between ARID1A‐mutant and ARID1A‐wildtype (WT) breast cancer samples to understand the transcriptional interplay between ARID1A and ARID1B." (PMID 40671262, 2025). "ARID1A regulated luminal cell identity in breast cancer and endocrine therapy response, by regulating genome-wide ER–FOXA1 chromatin interactions and ER-dependent transcription." (PMID 40406098, 2025). "Hyperactivated ARID1A/phospho-HDAC6/FOXM1 forms similar condensates in Ewing’s sarcoma or breast cancer recruiting BAFs complexes, Pol II, and coactivators to remodel chromatin structure that drive oncogenic transcription and tumor progression." (PMID 40507965, 2025). "ARID1A lies near a hot spot where multiple breast cancer breakpoints approximately aligned with breakage points in EBV-associated cancers." (PMID 39885374, 2025). "Elevated expression of ARID1B significantly decreased ARID1A levels in multiple breast cancer cell lines at both the protein and mRNA levels." (PMID 40671262, 2025). "This is supported by an in vitro migration assay study, which found that ARID1A effectively inhibits cell migration in multiple breast cancer cell lines." (PMID 41278204, 2025).
breast carcinoma (continued). "This developing understanding of ARID1A’s role in breast cancer not only highlights its implications for treatment but also broadens the landscape of cancer biology." (PMID 41514650, 2025). "A recent study found an increase of 6,197 BRD4-binding sites in ARID1A knockout breast cancer cells, indicating a significant increase in BRD4 chromatin binding activity." (PMID 41049615, 2025). "Breast cancer patients with low ARID1A expression, who have received radiotherapy (RT) demonstrated higher IL-6 expression compared to patients with high ARID1A expression." (PMID 38587186, 2024). "Breast Cancer: ARID1A not only exerts antitumor effects such as inhibiting cancer cell migration and invasion in breast cancer but also enhances the sensitivity of breast cancer cells to chemotherapy." (PMID 38893181, 2024). "The downregulation of phosphopeptides in genes like ARID1A, EPRS, and ZC3HAV1 in the high relapse-risk breast cancer group offers critical insights into their roles as tumor suppressors and regulatory molecules." (PMID 38745208, 2024). "Therapeutic strategies have been reported for ARID1A-mutant breast cancer based on synthetic lethality and cell dependency, such as some PARP, EZH2, and BRD4 inhibitors." (PMID 38365747, 2024). "After migration assays, it was found that ARID1A can effectively inhibit cell migration in multiple breast cancer cell lines." (PMID 38365747, 2024). "We induced DNA damage by IR of the ARID1A- depleted breast cancer cell line MDA-MB231 and observed increased accumulation of micronuclei, an indication for impaired DNA damage repair." (PMID 38587186, 2024). "Survival analysis of breast cancer patients showed better survival of patients with low ARID1A expression (group 1) when received RT." (PMID 38587186, 2024). "With CRISPR/Cas9 technology, scientists have found that breast cancer cells with ARID1A knockout had increased proliferation under estrogen deprivation conditions, compared to controls." (PMID 38365747, 2024). "While ARID1A loss has shown prognostic value for several neoplastic malignancies (e.g., gastric, lung, hepatocellular, and breast cancer), it remains ambiguous how ARID1A status influences the prognosis of gynecologic malignancies." (PMID 39272807, 2024). "Other genes that were frequently mutated in breast cancer included KMT2C, KMT2D, and ARID1A, which were involved in epigenetic regulation." (PMID 38539518, 2024). "ARID1A loss impairs SWI/SNF recruitment to regions of the genome that support luminal lineage commitment, thereby mediating a transition to basal-like breast cancer cells that are ER-independent." (PMID 37568822, 2023). "Specifically, ARID1A deletion or functional inactivation is associated with poor patient prognosis in metastatic luminal A and HER2-positive breast cancers, including endocrine therapy-resistant, ER-positive breast cancers." (PMID 37568822, 2023). "Our study included 2609 primary breast cancer samples from the TCGA and METABRIC datasets that were classified based on tumor subtype and the existence of mutations in PIK3CA and ARID1A genes." (PMID 38017109, 2023).
breast carcinoma (continued). "Loss of either ARID1A or BRG1 SWI/SNF subunits is frequently observed in diseases in which PGR expression is lost, including breast cancer, in which ARID1A is mutated in 5% of cases and ARID1A and BRG1 are known to play a role in response to ESR1 antagonists." (PMID 35326450, 2022). "In breast cancer, ARID1A impacts breast luminal lineage adherence and sensitivity to endocrine treatment." (PMID 36212140, 2022). "These two processes, ARID1A loss of function and enhanced PI3K/AKT signalling, are typically detected in endocrine-resistant breast cancer cells." (PMID 36212140, 2022). "Subsequently, we established stable EO771, MCF-7, and T47D clones overexpressing ARID1A respectively for further confirming that the expression level of ARID1A is crucial for eMDSCs to promote EMT of luminal A breast cancer cells." (PMID 36329699, 2022). "In this study, using in-house tissue array and TCGA dataset, we demonstrated that the infiltration of eMDSCs within breast cancer tissues affected the prognosis of luminal A breast cancer patients which was negatively correlated with ARID1A expression in situ." (PMID 36329699, 2022). "To further explore if downregulation of ARID1A expression is crucial for eMDSCs to promote EMT of luminal A breast cancer cells, we knocked down ARID1A by RNA interference and compared the expression of multiple functional genes by RT-PCR." (PMID 36329699, 2022). "In particular, AT-rich interactive domain-containing protein 1A (ARID1A), a member of the SWI-SNF family, was found to be mutated in gastric and pancreatic cancers and is related to breast cancer metastasis and indicative of trastuzumab resistance." (PMID 35267528, 2022). "We found that eMDSCs significantly downregulated ARID1A expression in luminal A breast cancer but the mechanistic events involved in this process are worth more consideration and exploration." (PMID 36329699, 2022). "Among the genetic abnormalities reported in ER+ breast cancer, mutations are commonly detected in genes encoding the subunits of the BAF chromatin remodeling complexes and ARID1A is the most frequently mutated one in BAF." (PMID 36329699, 2022). "This suggests that the combination of BET inhibitor and hormonal therapy is potentially effective against luminal breast cancer harboring mutant ARID1A." (PMID 35453496, 2022). "ARID1A is considered a prognostic marker in breast cancer with a higher level of metastatic incidence in patients with ARID1A mutations." (PMID 36078038, 2022). "That is why EZH2 in ARID1A mutant should be targeted as a powerful therapeutic strategy in breast cancer treatment." (PMID 35764927, 2022). "This discovery suggests that eMDSCs downregulated ARID1A expression via inducing mmu-miR-342-3p in EO771 cell and miRNA-related post-transcriptional regulation also participated in eMDSCs-induced ARID1A downregulation in luminal A breast cancer." (PMID 36329699, 2022). "As we previously identified the SWI/SNF complex as a key growth regulator in breast cancer cells, the induction of ARID1A in HME-hTert cells was confirmed by Western blots and the analysis of immunofluorescent staining." (PMID 36078038, 2022). "Bromodomain and extra-terminal motif (BET) inhibitors, including JQ1 and IBET762, exerted significant growth-inhibitory effects against ARID1A-null breast cancer." (PMID 35453496, 2022). "As ARID1A forms a complex with HDAC1, ARID1A mutation leads to the loss of HDAC1 function and promotes the progression of luminal breast cancer in a BRD4-dependent manner." (PMID 35453496, 2022). "This provides rational treatment strategies for inactivated ARID1A-mediated endocrine resistance in breast cancer." (PMID 34804958, 2021).